RNU6-1071P (RNA, U6 small nuclear 1071, pseudogene)
Gene: Small nuclear RNA gene on chromosome 1 (146,288,596 to 146,288,696, forward strand). Ensembl gene ENSG00000201789.
Homologues: Orthologues: chimpanzee U6 (99% identical), macaque U6 (96% identical), guinea pig U6 (83% identical), rat LOC120096740 (82% identical), pig U6 (76% identical), pig U6 (69% identical). Paralogues in human: RNU6-1171P (100% identical), RNU6-465P (100% identical), RNU6-1042P (91% identical), RNU6-891P (91% identical), RNU6-15P (90% identical), RNU6-698P (90% identical), RNU6-831P (90% identical), RNU6-1060P (89% identical), RNU6-1145P (89% identical), RNU6-116P (89% identical), RNU6-166P (89% identical), RNU6-25P (89% identical), and 1288 more.